CNN2 (calponin 2)
Description:
Thin filament-associated protein that is implicated in the regulation and modulation of smooth muscle contraction. It is capable of binding to actin, calmodulin and tropomyosin. The interaction of calponin with actin inhibits the actomyosin Mg-ATPase activity.
Tractability: Small molecule: it has a binding pocket of medium quality. Antibody: its Gene Ontology location is reachable by antibodies, with high confidence. PROTAC: ubiquitination databases record sites on it; its protein half-life has been measured.
Gene: Protein-coding gene on chromosome 19 (1,026,547 to 1,039,077, forward strand). Ensembl gene ENSG00000064666.
Subcellular location (Human Protein Atlas): Actin filaments
Pathways (Reactome):
Immune System: Gene and protein expression by JAK-STAT signaling after Interleukin-12 stimulation; Neutrophil degranulation
Gene Ontology:
Molecular function: cadherin binding; actin binding; actin filament binding
Biological process: cellular response to mechanical stimulus; regulation of actin filament-based process; actin filament organization; cytoskeleton organization; actomyosin structure organization
Cellular component: focal adhesion; membrane; stress fiber; actin cytoskeleton; cell-cell junction; cytoskeleton; extracellular region; specific granule lumen; tertiary granule lumen
Genetic constraint (gnomAD): Loss-of-function variants: 21 observed, 30.07 expected, observed/expected ratio (o/e) 0.7, 90% interval 0.49 to 1.01. The upper end of that interval is the gene's LOEUF score, 1.01, which puts it in group 4 of 6, group 1 being the genes least tolerant of losing a copy. Missense variants: 399 observed, 411.67 expected, observed/expected ratio (o/e) 0.97, 90% interval 0.89 to 1.05. Synonymous variants: 165 observed, 167.59 expected, observed/expected ratio (o/e) 0.98, 90% interval 0.87 to 1.12.
Homologues: Orthologues: macaque CNN2 (99% identical), mouse Cnn2 (95% identical), dog CNN2 (94% identical), guinea pig CNN2 (94% identical), pig CNN2 (94% identical), tropical clawed frog cnn2 (78% identical), rat Cnn2 (74% identical), zebrafish cnn2 (73% identical), Caenorhabditis elegans cpn-2 (23% identical), Drosophila melanogaster Chd64 (21% identical), Caenorhabditis elegans cpn-1 (20% identical), Drosophila melanogaster Mp20 (20% identical), and 2 more. Paralogues in human: CNN3 (66% identical), CNN1 (60% identical), TAGLN2 (28% identical), TAGLN3 (27% identical), TAGLN (26% identical).
Diseases named in the same sentence as CNN2 in open-access papers:
CNN2 is named in the same sentence as 51 diseases in open-access papers, as found by Europe PMC text mining. Sharing a sentence is not in itself a finding about the gene and the disease. The quoted sentences say what the papers report.
prostate carcinoma (9 papers, 2017 to 2024). A carcinoma that arises from epithelial cells of the prostate gland. "In prostate cancer cell lines, lower levels of calponin 2 were associated with faster proliferation, increased migration, and decreased substrate adhesion." (PMID 31569405, 2019). "In prostate cancer cells, Cnn2 has been reported as an androgen-responsive Srf target gene that affects cell migration." (PMID 37982489, 2023). "E, Differential gene and pseudogene expression for tumor and normal samples for each member of the CNN2/TAGLN2 PGG family in the prostate cancer TCGA dataset." (PMID 31029062, 2019). "Despite the wide distribution of calponin 2 in a variety of tissue types, its role in cancer biology has only been elucidated in the inhibition of prostate cancer metastasis." (PMID 28915602, 2017). "Previous studies have demonstrated that calponin 2 inhibits prostate cancer cell proliferation and metastasis." (PMID 28915602, 2017). "CNN2, an isoform of calponin proteins, which belong to a highly conserved family of actin-binding proteins, has been found in various cell types, such as smooth muscles, fibroblasts, endothelial cells, blood cells, and prostate cancer cells." (PMID 37982489, 2023). "For CNN2, this effect was also shown in fibroblasts and prostate cancer cells." (PMID 34074003, 2021). "CNN2 has been described in prostate cancer and is involved in cell migration and cell morphology." (PMID 28854272, 2017). "As a result, parent genes HTR7, CNN2, MSN, and TAGLN2 are DE; they generate pseudogenes, which are specifically expressed in prostate cancer samples." (PMID 31029062, 2019). "Calponin-2 has not been extensively studied in cancer, however, it was found to be a prognostic factor and to have tumor-suppressive effects in pancreatic and prostate cancers." (PMID 32887625, 2020). "Since calponin 2 inhibits PDAC cell proliferation and metastasis, its expression in tumor tissue is down-regulated as previously reported in metastasis versus non-metastasis prostate cancer cells." (PMID 28915602, 2017).
breast carcinoma (5 papers, 2017 to 2026). "It was also found that 10.5% of breast cancer patients had increased CNN2 expression in serum, suggesting that CNN2 can be used as a biomarker for the early diagnosis of breast cancer." (PMID 37373013, 2023). "In breast cancer cells, calponin 2 was also upregulated in comparison to that in normal breast gland cells." (PMID 28915602, 2017). "CNN2 has been found to be up-regulated in human breast cancer tissues but not in healthy and benign controls according to proteomic analysis." (PMID 37373013, 2023). "However, a weak amplification band appeared in the breast cancer cells, while in the normal human hepatocytes, no CNN2 mRNA expression was found." (PMID 37373013, 2023).
hepatocellular carcinoma (3 papers, 2021 to 2023). A malignant tumor that arises from hepatocytes. "For example, it has been revealed that NEAT1 promotes the development of hepatocellular carcinoma cells via regulating the miR-296-5p/CNN2 axis." (PMID 33281971, 2021).
pancreatic ductal adenocarcinoma (3 papers, 2017 to 2023). An infiltrating adenocarcinoma that arises from the epithelial cells of the pancreas. "In pancreatic ductal adenocarcinoma, a higher level of calponin 2 expression was associated with reduced lymph node metastasis and prolonged postsurgical survival time." (PMID 31569405, 2019). "Here, we demonstrate that the level of calponin 2 is a positive prognostic factor for patients with pancreatic ductal adenocarcinoma (PDAC)." (PMID 28915602, 2017). "In pancreatic ductal adenocarcinoma, the high expression of CNN2 was found to be significantly associated with less lymph node metastasis and longer survival of patients, suggesting its tumor-suppressing functions." (PMID 37188478, 2023).
atherosclerosis (2 papers, 2020 to 2022). A disease characterized by the build-up of fatty material and calcium deposition in the arterial wall resulting in partial or complete occlusion of the arterial lumen. "For example, rabbits lack calponin 2, an actin-associated cytoskeletal protein that is important in the pathogenesis of inflammatory arthritis, atherosclerosis, and calcific aortic valve disease." (PMID 32185166, 2020). "The loss of calponin 2 in myeloid immune cells in mice has been shown to modulate inflammatory responses, such as attenuating inflammatory arthritis and the pathogenesis of atherosclerosis." (PMID 32185166, 2020).
calcific aortic valve disease (2 papers, 2020 to 2023). "CNN2 was also reported to be capable of regulating functions of myofibroblasts, thus highlighting its potential in the treatment and prevention of the calcific aortic valve disease." (PMID 37188478, 2023). "CNN2 knock out in mice also reduces myofibroblast differentiation and the development of calcific aortic valve disease and slows down platelet adhesion in thrombosis." (PMID 32185166, 2020).
colorectal cancer (2 papers, 2023). A primary or metastatic malignant neoplasm that affects the colon or rectum. "Relationship between CNN2 expression and tumor characteristics in patients with colorectal cancer." (PMID 37188478, 2023). "In this study, we utilized SEREX technology to examine the presence of CNN2 antibodies in the serum of individuals with HCC, gastric cancer, lung cancer, colorectal cancer, hepatitis, cirrhosis, and healthy individuals." (PMID 37373013, 2023). "In colorectal cancer (CRC), CNN2 was found to form a complex with YAP1 and EGR1, thus regulating EGR1 expression and promoting CRC, which could be considered as a potential therapeutic target for CRC." (PMID 37188478, 2023).
follicular lymphoma (2 papers, 2025). Follicular lymphoma is a form of non-Hodgkin lymphoma characterized by a proliferation of B cells whose nodular structure of follicular architecture is preserved. "CNN2 enhances the development of follicular lymphoma cells by inducing their migration and invasion." (PMID 41296384, 2025). "Among them, CNN2 is involved in the regulation of the development of follicular lymphoma." (PMID 41296384, 2025). "Furthermore, a four-gene panel comprising CNN2, HMG20B, ACRBP, and IZUMO1 successfully distinguished DLBCL from follicular lymphoma (FL), achieving an AUC of 0.89 in the testing set, regardless of the cell-of-origin or stage of DLBCL." (PMID 40055844, 2025).
gastric cancer (2 papers, 2023). A primary or metastatic malignant neoplasm involving the stomach. "In gastric cancer, a typical loss-of-function study made on CNN2 revealed the suppression of tumor development upon CNN2 silence." (PMID 37188478, 2023). "The HCC group exhibited a significantly higher positive rate of anti-CNN2 antibody (54.8%) compared to gastric cancer (6.5%), lung cancer (3.2%), rectal cancer (9.7%), hepatitis (3.2%), liver cirrhosis (3.2%), and normal tissues (3.1%)." (PMID 37373013, 2023). "RT-PCR was used to detect the mRNA expression of CNN2 in tumor cells, and strong expressions were amplified in the HCC, gastric cancer, and lung cancer cell lines." (PMID 37373013, 2023). "The positive rate of CNN2 mRNA expression in lung cancer, HCC, gastric cancer, and nasopharyngeal cancer was 17.5% (7/40 cases), 50.0% (27/54 cases), 10.0% (4/40 cases), and 20.0% (8/40 cases), respectively." (PMID 37373013, 2023). "The positive rate of CNN2 protein expression in lung cancer, HCC, gastric cancer, and nasopharyngeal carcinoma was 17.5% (7/40 cases), 51.8% (28/54 cases), 27.5% (11/40 cases), and 45% (18/40 cases), respectively." (PMID 37373013, 2023). "Our results show that the positive rate of CNN2 antibody in the HCC patients was 54.8%, which was significantly higher than that in the gastric cancer (6.5%), lung cancer (3.2%), rectal cancer (9.7%), hepatitis (3.2%), cirrhosis (3.2%), and normal tissue samples (3.1%) (p < 0.05)." (PMID 37373013, 2023). "The positive rates of CNN2 mRNA in HCC with metastasis, non-metastatic HCC, lung cancer, gastric cancer, nasopharyngeal cancer, liver cirrhosis, and hepatitis were 56.67%, 41.67%, 17.5%, 10.0%, 20.0%, 53.13%, and 41.67%, respectively." (PMID 37373013, 2023).
liver cancer (2 papers, 2022 to 2023). An epithelial or non-epithelial malignant neoplasm that arises from the liver. "When we silenced CNN2 expression in HepG2 cells, the cell scratch and cell migration assay showed that suppressing the expression of CNN2 significantly hindered the migration and invasion of liver cancer cells." (PMID 37373013, 2023). "The motility of liver cancer cells was evaluated through a scratch-healing experiment after CNN2 silencing with CNN2-siRNA1." (PMID 37373013, 2023). "This study demonstrates that CNN2 exhibited high expression levels in the serum, liver cancer cells, and tumor tissues of HCC patients, with significantly increased levels in metastatic HCC." (PMID 37373013, 2023). "The scratch width between these two groups showed statistical significance (p < 0.05), suggesting that CNN2-siRNA was capable of inhibiting the motility and migration of liver cancer cells." (PMID 37373013, 2023). "Hsa-miR-296-5p is reduced in liver cancer tissues and cell lines and its overexpression inhibited liver cancer progression via directly targeting CNN2." (PMID 35590240, 2022). "Our previous research also demonstrated that CNN2 plays a critical part in tumor growth and metastasis, and it may serve as a potential target for molecular-targeted therapy of liver cancer." (PMID 37373013, 2023). "CNN2 is a newly identified HCC-associated antigen that is implicated in the migration and invasion of liver cancer cells, making it a promising target for liver cancer therapy." (PMID 37373013, 2023). "The down-regulation of CNN2 could inhibit the migration and invasion of liver cancer cells." (PMID 37373013, 2023). "We found that CNN2 was highly expressed in liver cancer cell lines, but not in normal liver cell lines." (PMID 37373013, 2023). "There was no CNN2 mRNA or protein expression detected in the normal hepatocytes (L-O2) by the RT-PCR or Weston blot methods, while there were strong expression bands in the liver cancer cells." (PMID 37373013, 2023). "Therefore, CNN2 may be used as a biomarker of HCC rather than a marker of other liver cancer diseases." (PMID 37373013, 2023).
lymph node metastasis (2 papers, 2017 to 2019). "Higher expression of calponin 2 predicts favorable survival and correlates with less lymph node metastasis." (PMID 28915602, 2017). "Patients with high calponin 2 expression in the tumor presented less lymph node metastasis and longer survival." (PMID 28915602, 2017). "Patients without lymph node metastasis had a higher ratio (63%) of high calponin 2 expression than that of those with positive lymph node metastasis (34%)." (PMID 28915602, 2017). "The expression of calponin 2 was negatively correlated with lymph node metastasis." (PMID 28915602, 2017). "Calponin 2 expression was negatively correlated with lymph node metastasis, but not with gender, age, location, differentiation, depth of invasion or TNM stage." (PMID 28915602, 2017). "The variables of gender, age, location, differentiation, depth of invasion, lymph node metastasis, TNM stage and calponin 2 expression were included in the analysis and the results showed that calponin 2 expression had statistically significant beneficial effect on survival P < 0.05." (PMID 28915602, 2017).
renal fibrosis (2 papers, 2020 to 2025). A final common manifestation of a wide variety of chronic kidney diseases characterized by glomerulosclerosis and tubulointerstitial fibrosis. "CNN2 deficiency can upregulate CPT1A and other key enzymes through ESR2-PPARα axis, promote FAO and reduce renal fibrosis after RIRI." (PMID 41451126, 2025).
acute kidney injury (1 paper, 2023). Sudden and sustained deterioration of the kidney function characterized by decreased glomerular filtration rate, increased serum creatinine or oliguria. "However, whether CNN2 is actively involved in acute kidney injury (AKI) remains unclear." (PMID 37751293, 2023). "Therefore, it would be worthwhile to fully dissect the role of CNN2 in acute kidney injury (AKI), given that AKI and CKD are closely intertwined but have distinct pathogenesis." (PMID 37751293, 2023).
aneurysm (1 paper, 2023). Bulging or ballooning in an area of an artery secondary to arterial wall weakening. "The otherwise reduced expression level of the marker genes of contractile VSMCs (including Myocd, Srf, Myh11, Cnn1, Cnn2, and Tagln) in aneurysms was rescued in FAM3A-overexpressing aortas." (PMID 37660071, 2023).
aortic valve disease (1 paper, 2023). "Earlier studies demonstrated that deleting CNN2 attenuates calcific aortic valve disease by reducing myofibroblast differentiation, and deleting CNN2 in fibroblasts further increases myosin II–dependent cell traction force." (PMID 37751293, 2023).
autoimmune disease (1 paper, 2023). A disorder resulting from loss of function or tissue destruction of an organ or multiple organs, arising from humoral or cellular immune responses of the individual to their own tissue constituents. "Two of the families (3 and 8) were consanguineously related by the third degree, and were the only families that were associated with the CNN2 gene, linked to the innate immune system and autoimmune diseases." (PMID 36979105, 2023).
cardiac hypertrophy (1 paper, 2016). "Specifically, markers of non-cardiac differentiation, such as those for vascular endothelium (VWF) and non-cardiac muscle (CDH6, CNN2 and MYLK) were downregulated, while genes encoding for cardiac hypertrophy (IGF1R) and calcium handling (CAMK2B) were upregulated." (PMID 26785135, 2016).
chronic kidney disease (1 paper, 2023). Impairment of the renal function secondary to chronic kidney damage persisting for three or more months. "In chronic kidney disease (CKD), CNN2 regulates energy metabolism by interacting with estrogen receptor 2 (ESR2) to control fibrosis progression." (PMID 37751293, 2023).
Cirrhosis (1 paper, 2023). A chronic disorder of the liver in which liver tissue becomes scarred and is partially replaced by regenerative nodules and fibrotic tissue resulting in loss of liver function. "The results indicate that the positive rate of anti-CNN2 antibodies in the HCC patients’ serum was significantly higher than that in the patients with cirrhosis or the normal controls." (PMID 37373013, 2023). "This means that the positive detection of anti-CNN2 antibody in the serum cannot be attributed to factors such as age, gender, AFP value, pathological grade, presence of cirrhosis, ALT value, AST value, HBsAg, and tumor size." (PMID 37373013, 2023). "We coated the ELISA plate with the purified CNN2 recombinant protein and detected the presence of CNN2 antibody in the serum of patients with primary HCC, hepatitis cirrhosis, and normal tissue by the indirect ELISA method." (PMID 37373013, 2023).
colon cancer (1 paper, 2023). "Similarly, there have also been studies showing that the expression of CNN2 is related to the invasion ability of colon cancer, and a high level of CNN2 expression has been detected in colon cancer tissues." (PMID 37373013, 2023).
COVID-19 (1 paper, 2026). A disease caused by infection with severe acute respiratory syndrome coronavirus 2. "Therefore, we propose that SARS-CoV-2 damages mucosal epithelium integrity via a novel "double hijack" mechanism: inducing dedifferentiation and disrupting stratification and suggest a new therapeutic target: CNN2 for COVID-19 treatment." (PMID 41872170, 2026). "Moreover, CNN2 levels were elevated in the epithelia of COVID-19 patients." (PMID 41872170, 2026).
depression (1 paper, 2025). "Our results are in opposite direction compared to previous studies showing the association of upregulated CNN2 with depression and psychosis in human and animal studies." (PMID 40473930, 2025).
Hepatitis (1 paper, 2023). Inflammation of the liver. "The positive rates of CNN2 protein expression detected by immunohistochemistry were 37.5% (12/32) in non-metastasis HCC, 63.3% (19/30) in HCC with metastasis, 20.8% (5/24) in hepatitis, and 31.3% (10/32) in liver cirrhosis, respectively." (PMID 37373013, 2023). "Positive rates of CNN2 mRNA expression detected by in situ RT-PCR were 41.67% (10/24 cases) in non-metastasis HCC, 56.67% (17/30 cases) in HCC with metastasis, 41.67% (10/24 cases) in hepatitis and 53.13% (17/32 cases) in liver cirrhosis." (PMID 37373013, 2023). "There was a statistically significant difference in the positive rate of CNN2 protein between HCC with metastasis and hepatitis, liver cirrhosis tissues (p < 0.05), but no significance was found between non-metastasis HCC, hepatitis, and liver cirrhosis tissues (p > 0.05)." (PMID 37373013, 2023).
liposarcoma (1 paper, 2007). A usually painless malignant tumor that arises from adipose tissue. "Genes highly expressed in the dedifferentiated/pleomorphic liposarcomas included cell-cycle genes like CCNA2, CCNB2, CDC2, KIFC1, KIF23 and PTTG1, motility genes like AMFR, ANXA1, CKB, CNN2 and FN1 and homeostasis-related genes." (PMID 17359542, 2007).